RNU6V (RNA, U6 small nuclear variant sequence with SNRPE pseudogene sequence)
Synonyms: 87U6; LH87
Gene: Small nuclear RNA gene on chromosome 1 (109,591,534 to 109,591,640, reverse strand). Ensembl gene ENSG00000206832.
Homologues: Orthologues: chimpanzee U6 (98% identical), guinea pig U6 (84% identical), dog U6 (73% identical). Paralogues in human: RNU6-16P (93% identical), RNU6-1 (92% identical), RNU6-2 (92% identical), RNU6-39P (92% identical), RNU6-3P (92% identical), RNU6-45P (92% identical), RNU6-4P (92% identical), RNU6-5P (92% identical), RNU6-6P (92% identical), RNU6-9 (92% identical), RNU6-968P (92% identical), RNU6-10P (91% identical), and 1287 more.